BCL6 (BCL6 transcription repressor)
Diseases named in the same sentence as BCL6 in open-access papers (continued):
Sharing a sentence is not in itself a finding about the gene and the disease.
lymphoma (continued). "To avoid confounders in the outcome and biomarker analysis, we first analyzed the outcome of patients with MYC/BCL2 and/or BCL6 double-hit lymphoma (N = 7)." (PMID 40166656, 2025). "To investigate the effects of resveratrol on the proliferation of GC-derived NHL, we conducted MTS assays using a panel of BCL6-dependent lymphoma cell lines, including DLBCL (SUDHL4 and Farage), BL (Ramos and Raji), and FL (DOHH2)." (PMID 39815148, 2025). "Since BCL6 is a key regulator of malignant B cell growth, most studies on pharmacologically targeting BCL6 are aimed at eliminating BCL6-expressing lymphomas in vivo." (PMID 41246349, 2025). "To determine the in vivo target engagement by IACS-16898, we measured the levels of B-cell lymphoma 6 (BCL6), an established lymphoma oncogenic driver amplified in DOHH2 cells." (PMID 41290625, 2025). "CDKN1A, a pivotal regulator of the cell cycle, is directly repressed by BCL6 to enable unchecked cellular proliferation, thereby driving the rapid expansion of lymphoma cells." (PMID 39815148, 2025). "In the orbital lesions on both sides of the present patient, lymphoma cells were positive for BCL6, which would be used to be differentiated from marginal zone B-cell lymphoma." (PMID 40896064, 2025). "BCL6 has been reported to co-regulate GC formation and lymphoma cell survival with EZH2 and PRMT5, respectively." (PMID 39815148, 2025). "These included six lymphoma lines with high, medium, and low levels of BCL6 expression and one leukemia cell line (K562) with negligible BCL6." (PMID 40166243, 2025). "Fluorescence in situ hybridization (FISH) is a cornerstone diagnostic tool in lymphoma, serving as the gold standard for detecting specific gene rearrangements, including MYC, BCL2, and BCL6, as well as gene fusions such as IGH::MYC and IGH::BCL2." (PMID 41010038, 2025). "Standard histological examination depends on tissue availability and is currently supplemented with molecular tests, as the status of MYC, BCL2, or BCL6 gene rearrangements is required for proper lymphoma classification." (PMID 39905397, 2025). "BCL6-high expressing cells SUDHL5 and K422 displayed more pronounced c-MYC repression following a 1 nM TCIP3 treatment than BCL6-low lymphoma cells OCILY19 and TOLEDO, or the leukemia line K562." (PMID 40166243, 2025). "According to Hans’ criteria, cases are classified using IHC as the GCB subtype if lymphoma cells were CD10+ or CD10− Bcl6+ MUM−." (PMID 40365164, 2025). "For the differential diagnosis of other lymphomas, the immunohistochemical staining of Bcl-6 (+++), ki-67 (+++), c-myc (+), Pax-5 (++), MUM1 (+), CD5(+), and CD10 (−) was performed." (PMID 40453362, 2024). "Degradation of BCL6 promotes significant induction of expression of BCL6-repressed genes and antiproliferative effects BCL6-dependent lymphoma cell lines." (PMID 38165043, 2024). "Using cell numbers as a proxy for disease prognosis resulted in predictions that MYC + BCL2 DH lymphoma would have worse prognosis than MYC + BCL6 DH lymphoma." (PMID 38965209, 2024). "Consistent with our immunohistochemistry findings, elevated Bcl6 and c-Myc expression was observed in lymphoma-bearing mLNs from Fbw7ΔEC mice, compared with normal mLNs from WT mice." (PMID 38485719, 2024). "A subtype of lymphomas is called a double-hit lymphoma, which forms when it contains MYC and either BCL2 or BCL6 mutations; this subtype is often seen in patients who have disease at the interference between Burkitt lymphoma and DLBCL." (PMID 39010207, 2024). "WHO-HAEM5 separates DLBCL/HGBCL with MYC and BCL2 rearrangements from the previous entity—HGBCL with MYC and BCL2 and/or BCL6 rearrangements, also known as “double-hit”/“triple-hit” (DH/TH) lymphomas." (PMID 39518937, 2024). "The World Health Organization (WHO) classifies DLBCL with MYC and BCL2 rearrangements and the simultaneous occurrence of BCL6 gene rearrangement as double-hit lymphoma (DHL) or triple-hit lymphoma (THL)." (PMID 38381215, 2024).
lymphoma (continued). "In cases with morphological features intermediate between BL and DLBCL, FISH analysis for MYC, BCL2 and BCL6 rearrangements allows the correct differential diagnosis among BL, DH/TH lymphomas and HGBCL, NOS." (PMID 39684922, 2024). "Although BCL6 small-molecular inhibitors show promise as therapeutic targets for human lymphomas, the BCL6-mediated regulatory networks in EBV-transformed LCLs remain elusive." (PMID 38864622, 2024). "These patients have previously been published as part of a prior study (n = 34) investigating MYC, BCL2, and BCL6 rearrangements, pathogenic variants of MYD88 and CD79B, and double-expressor lymphoma." (PMID 38542066, 2024). "As BCL-6 is a key TF for GC reaction, its dysregulation is also involved in the pathogenesis of GC-derived lymphomas." (PMID 36817488, 2023). "This approach enabled the clustering of lymphomas with co-occurring MYD88- and CD79B mutations (MCD), BCL6 rearrangements and NOTCH2 mutations (BN2), EZH2 mutations and BCL2 rearrangements (EZB), as well as NOTCH1 mutations (N1)." (PMID 38124747, 2023). "BCL2, MYC, and/or BCL6 are simultaneously rearranged in so-called double-hit and triple-hit lymphomas, respectively." (PMID 37371852, 2023). "With the in-depth study of BCL6 and hematological tumors such as lymphoma in recent years, it has been revealed that BCL6 is closely related to various solid tumors such as breast cancer and lung cancer, and played various roles in different tumors." (PMID 37060074, 2023). "So-called double-hit lymphomas usually carry BCL2 and MYC rearrangements, while triple-hit lymphomas additionally bear BCL6-fusions." (PMID 37371852, 2023). "PRMT5 contributed to the disease by methylating BCL6 at R305, which is necessary for the full transcriptional repressive effects of BCL6 in lymphoma." (PMID 37461162, 2023). "Nonetheless, all the peripheral blood samples in this study were acquired before 2022, and we still considered the DLBCL with MYC and BCL2 and/or BCL6 rearrangement as DHL/THL according to the 2016 World Health Organization classification of lymphoma." (PMID 36823603, 2023). "Elevated Peli1 expression induces lymphoma development by facilitating B-cell lymphoma 6 (BCL6) ubiquitination through K63 linkage and promoting the constitutive activation of the post-BCL6 B-cell signaling pathway." (PMID 38179042, 2023). "ASTCT recommends upfront auto‐HSCT only with c‐myc and bcl‐2 and/or bcl‐6 rearrangements (high‐grade lymphomas)." (PMID 36855295, 2023). "While TFAP4 was an essential gene in 48% of the cell lines and BCL6 was a lymphoma-specific essential gene, the other 6 in vivo hits showed little evidence of depletion across all cancer types, including 9 osteosarcoma cell lines." (PMID 37938582, 2023). "For patients who were diagnosed with DLBCL or BL, MYC, BCL2, and BCL6 rearrangements should be detected by FISH to exclude double/triple-hit lymphoma." (PMID 37182167, 2023). "Fluorescence in situ hybridization studies for MYC and BCL2 and/or BCL6 rearrangements were performed in 27 patients, and only one patient had double‐hit lymphoma." (PMID 37997571, 2023). "Although this lymphoma is more frequently observed in children and young adults, cases in adults share the GCB-type, IRF4 mutations, and frequent coexpression of CD10, BCL6, and MUM1." (PMID 36810796, 2023). "Most germinal center-derived lymphomas depend on the expression and transcriptional activity of BCL6." (PMID 37060074, 2023). "Immunohistochemical results for lymphoma cells of left cervical lymph nodes were as follows: BCL6 (+), MUM1 (+), Ki-67 (80%+), CD20 (+), Pax5 (+), BCL2 (+), CD10 (+), CyclinD1 (-), and sparsely positive for CD3, CD5, CD15, CD30, CD68, and C-MYC." (PMID 38143763, 2023). "A subgroup of PTCL-NOS cases was recently subclassified into a distinct subgroup as PTCL-TFH, consisting of lymphomas which were observed to manifest a T follicular helper cell phenotype including TFH-related antigens such as BCL6, CCR5, CD10." (PMID 36776886, 2023).
lymphoma (continued). "Aberrant genomic or expressional changes of BCL6 have been detected in lymphomas and multiple solid tumors, including breast cancer, glioblastoma or ovarian cancer." (PMID 35503721, 2022). "The BCL6 transcriptional program for the direct silencing of multiple target genes has been elaborated in primary B cells and lymphoma." (PMID 35503721, 2022). "It is then conceivable that LVBU’s positive impact on BCL6 will lead to tumorigenesis such as the case in lymphoma." (PMID 35906392, 2022). "Both inhibitors and degradersof BCL6 have been shown to cause selective growth inhibition in BCL6-drivenlymphoma cell lines, but to date, the therapeutic potentialof inhibition or degradation of BCL6 in vivo in lymphomas has notbeen thoroughly tested." (PMID 35657291, 2022). "Therapy targeting the BCL6 BTB domain lateral groove displayed inhibitory effects in the treatment of lymphoma." (PMID 35503721, 2022). "The MEF2B gene mutation results in enhanced transcriptional activity, increased BCL6 expression, drives lymphomagenesis in mouse model, led to GC enlargement and lymphoma development." (PMID 35883106, 2022). "The double-hit status (simultaneous translocations of MYC and BCL2 or BCL6) was determined in 146 lymphomas, with a positive result in 11 cases (7.5%)." (PMID 34708297, 2022). "During lymphomagenesis, hypermethylation of the first intron DNA blocks CTCF binding, thereby allowing the enhancer to exert its effects and increase BCL6 expression, promoting the development of lymphoma." (PMID 36443876, 2022). "Initiation and formation of GCs is regulated by expression of several factors, among them MYC, B-cell lymphoma 6 (BCL6) and E2A, which are often dysregulated in GC-derived lymphomas." (PMID 36428647, 2022). "Chromosomal translocations juxtaposing the oncogenes MYC, BCL2, or BCL6 and one of the immunoglobulin loci are hallmarks in the genesis of lymphomas." (PMID 35060000, 2022). "Together with possible anti-BCL6 effects, the anti-inflammatory effects of Lifitegrast would serve well for lymphoma therapy." (PMID 36473934, 2022). "The 5th edition of the WHO classification of haemato-lymphoid tumors 2022 acknowledges these similarity relations between the lymphoma entities and segregates DH BCL6 as a subtype of DLBCL, NOS or HGBL, NOS apart from the DH BCL2." (PMID 35884496, 2022). "This suggests that LSD1 plays a key role in lymphangiogenesis as an important BCL6 cofactor, as this classical lymphoma oncogene requires LSD1 to induce malignant transformation." (PMID 35463343, 2022). "B-cell lymphoma 6 (BCL6) regulates various genes and is reported to be overexpressed in lymphomas and other malignancies." (PMID 36473934, 2022). "The authors performed structural studies (broad complex, Tramtrack, Bric-a-Brac) to find an appropriate Bcl6 BTB domain-binding compound BI-3802 that degraded Bcl6 in human GCB-type DLBCL lymphoma cell lines at nanomolar concentrations." (PMID 35954440, 2022). "Differently, the fewer lymphomas developed in Faslpr/lpr animals showed a strong positivity for BCL6, a classical marker of human GCB-DLBCLs, and negligible expression of the ABC-related proteins." (PMID 36503430, 2022). "FBXO10 and FBXO11 bind to BCL2 and BCL6, respectively, resulting in their ubiquitination and promoting their degradation, thereby regulating the levels of BCL2 and BCL6 proteins in lymphoma cells." (PMID 36644760, 2022). "The anti-inflammatory effects of Lifitegrast, in combination with its BCL6 inhibitory effects, promise an amenable drug candidate for lymphoma treatment." (PMID 36473934, 2022).
lymphoma (continued). "The World Health Organization (WHO) classification considers cases with concurrent MYC and BCL2 and/or BCL6 rearrangement determined by fluorescence in situ hybridization (FISH) as “double-hit” lymphomas (DHL) or “triple-hit” lymphomas (THL), respectively." (PMID 35198451, 2022). "The signal transduction protein STAT5 serves as a negative regulator of BCL6 in lymphomas, and FoxO3a promotes BCL6 expression in leukemia cells exposed to BCR-ABLi." (PMID 36377663, 2022). "These lymphomas are often called double-hit lymphomas, or triple-hit lymphomas if there are both Bcl-2 and Bcl-6 rearrangements in addition to the MYC rearrangement." (PMID 36618391, 2022). "This also suggests the need for a different treatment approach than is obtained in the West where BCL6 double hit lymphomas are seemingly GCB." (PMID 33807449, 2021). "“Double-hit” (with MYC, BCL2, or BCL6 alterations) and “triple-hit” (with MYC, BCL2, and BCL6 alterations) lymphomas are also aggressive in nature, and are part of the high-grade B-cell lymphomas." (PMID 34947882, 2021). "Analysis of BL and DLBCL tumors revealed that apart from the IG genes, main loci of AID mutations were active enhancers of genes with a known role in lymphoma: BCL6, PAX5, ETS1, CIITA, CXCR4." (PMID 34210001, 2021). "The presence of rearrangements in all three of the genes (MYC, BCL2 and BCL6) characterizes a further subgroup of high-grade lymphomas called triple-hit lymphoma." (PMID 34943410, 2021). "LSD1 is found to be essential for germinal centers (GC) formation and humoral immune response by interacting with B-Cell Lymphoma 6 Protein (BCL6) in lymphoma cells." (PMID 34491469, 2021). "Unlike in the West, the majority of patients with multiple hit lymphoma in Taiwan harbor a BCL6 rearrangement." (PMID 33807449, 2021). "Another important consideration is the presence of genetic rearrangements of the MYC, BCL2, and BCL6 genes that identifies patients with what is called double- or triple-hit lymphomas (MYC with BCL2 and/or BCL6 rearrangements)." (PMID 34945817, 2021). "Focusing instead on differential chromatin interactivity, we found a significant bias towards reduction in chromatin loop strength in Smc3/Bcl6 vs Bcl6 lymphomas." (PMID 34621263, 2021). "A major impact on lymphoma formation has the lysine demethylase LSD1 as it interacts with BCL-6 to repress B-cell termination." (PMID 35008680, 2021). "In leukemia and lymphoma, BCL6 orchestrates BACH2 protein stability and the balance of the BCL6/BACH2 axis is essential in regulating pre B-cell receptor checkpoint cascades." (PMID 32085659, 2020). "Overall, by 20 months of age, 76–89% of BCL6-overexpressing mice had either lymphoproliferative disease or lymphoma (compared to 8–14% in wild-type mice), as well as a significant decrease in survival." (PMID 33277464, 2020). "FL can also transform into a composite lymphoma, combining a HGBL with BCL2 and/or BCL6 and MYC rearrangements, and a B-ALL characterized by a loss of maturity markers, such as CD20 and surface immunoglobulins." (PMID 32713346, 2020). "Treatments with compounds that disrupt the interaction between BCL6 and the co-repressor complex have been shown to relieve suppression of BCL6 target genes and inhibit growth of lymphoma cells in vitro." (PMID 32180900, 2020). "One double-hit lymphoma of BCL6/C-MYC was established in DLBCL Case 6, however both of the BCL6/C-MYC protein expression showed less than 50% and 40% respectively with Ki67 of 40%." (PMID 31892985, 2020). "High-grade B-cell lymphomas with MYC and BCL2 and/or BCL6 rearrangements represent a quite recently defined entity of lymphoma with aggressive nature, high genomic complexity and poor prognosis." (PMID 33339535, 2020). "Due to this anti-apoptotic activity BCL6 is a strong oncogene, with ectopic expression in B-cells a key driver event in lymphoma." (PMID 32320427, 2020).
lymphoma (continued). "BCL6 is a central mediator of germinal center formation and has been suggested as a therapeutic target in lymphoma." (PMID 32264925, 2020). "Pharmacokinetic properties, however, limit the use of these BCL6-degrading compounds in vivo, such that the effect of BCL6 degradation on in vivo growth of lymphoma cells cannot be studied." (PMID 32180900, 2020). "These malignancies are also known as double-hit (MYC/BCL2 or MYC/BCL6 translocations) and triple-hit (MYC/BCL2/BCL6 translocations) lymphomas (DHL/THL), and represent 5–10% of DLBCL patients." (PMID 33260693, 2020). "Diffuse large B cell (DLBCL) and high grade B cell lymphomas (HGBL) demonstrating MYC translocation with concurrent BCL2 and/or BCL6 rearrangements, colloquially called double and triple hit lymphomas (DHL and THL), have poor clinical outcomes." (PMID 31932576, 2020). "Specific oncogenes, such as MYC, BCL-2, and BCL-6, converge proliferation, differentiation, and anti-apoptotic signaling in lymphoma cells and play critical roles in lymphomas." (PMID 32296035, 2020). "While translocations in MYC, BCL2, and BCL6 represent significant genomic events in lymphoma, less is known about the contribution of chromosomal copy number alterations (CNAs) in these genes to existing translocations." (PMID 33168821, 2020). "With regards to double or triple aberrations among the three genes, our study had one double-hit lymphoma of BCL6/C-MYC found in DLBCL Case 6, with both of the BCL6/C-MYC protein expression showing less than 50% and 40% respectively and Ki67 of 40%." (PMID 31892985, 2020). "Chemically induced degradation of Bcl-6 by small molecules, such as BI-3802, have been found to have stronger effects than Bcl-6 inhibition and thus offer new routes to the development of lymphoma treatments." (PMID 32718354, 2020). "BCL6 inhibition has been shown to be highly effective in animal models of lymphoma and leukemia, and several inhibitors are currently in clinical development." (PMID 32320427, 2020). "The oncogene B-cell lymphoma 6 (BCL6), which is a crucial regulator of B-lymphocyte development, is a transcriptional modulator and often deregulated in lymphomas." (PMID 33182312, 2020). "First, apoptosis induced by chemotherapeutic agents was prevented by BCL6 over-expression in lymphoma cell lines." (PMID 32320427, 2020). "Immunohistochemical studies confirmed that all lymphomas expressed BCL6, CD10, and CD23, and most expressed variable BCL2." (PMID 32555149, 2020). "In comparison, the reference HDAC inhibitor, SAHA, only marginally reduced the expression of the poor prognostic factors of MYC, BCL-2, and BCL-6 in the tested lymphoma cell lines." (PMID 32575557, 2020). "Previous work showed that BCL6 can form a transcriptional repressor complex with MIZ1 that represses CDKN1A expression in GC-derived lymphoma cell lines." (PMID 32407433, 2020). "The 2016 WHO classification recognizes and categorizes high‐grade B‐cell lymphomas (HGBCL) with MYC and BCL2 and/or BCL6 gene rearrangements as a separate entity, commonly referred to as “double‐hit” lymphomas." (PMID 31659781, 2020). "In summary, this indicates that targeting of BCL6 represents a viable strategy for lymphoma treatment." (PMID 32180900, 2020). "Our study identifies a unique set of cases that have concurrent translocations and copy number gains in MYC, BCL2, and/or BCL6 outside of DH/TH lymphoma that cannot readily be identified using standard FISH alone." (PMID 33168821, 2020). "Our findings support a role of BCL6 in the maintenance of lymphoma growth and showcase the utility of inducible CRISPR/Cas9 systems for probing oncogene addiction." (PMID 32180900, 2020). "Romidepsin showed anti-cancer activity via BCL-6 suppression in lymphoma, and now the compound is in clinical trials for combination therapies with various agents." (PMID 32575557, 2020). "In lymphoma, BCL6 is involved in epigenetic reprogramming of its targets through interacting with both PRC1 and PRC2 complexes." (PMID 31380371, 2019).